DRD2 (dopamine receptor D2)
Diseases named in the same sentence as DRD2 in open-access papers (continued):
Sharing a sentence is not in itself a finding about the gene and the disease.
migraine (22 papers, 2009 to 2025). "Multiple epidemiological studies have investigated the association between migraine susceptibility and polymorphisms of the four genes DRD2, COMT, DBH, and MAO-A." (PMID 26632697, 2015). "In population 1, a five-marker risk haplotype in the DRD2 gene and a single variant in the TH gene were found to be associated with migraine, and both remained significant after applying correction for multiple comparisons." (PMID 19772578, 2009). "It is worth mentioning, however, that a (TG)n repeat variant in DRD2 was found associated with yawning and nausea in a small subgroup of migraine patients." (PMID 19772578, 2009). "Moreover, the DRD2 agonist associated with migraine relief has been mechanistically linked to the regulation of AMPA receptor trafficking via a PI3K, Src family kinases (SFKs), pathway in a rat model of migraine." (PMID 40634879, 2025). "Natural DRD2 ligands, including dopamine and trace amines like tyramine, exert influence on DRD2 function, potentially impacting neurotransmitter release and neuronal excitability relevant to migraine pathogenesis and depressive symptoms." (PMID 40634879, 2025). "One of the earliest identified common mechanistic links on this front is the involvement of dopamine receptor, DRD2, which provided one of the first genetic linkages between migraine and MDD." (PMID 40634879, 2025). "DRD2 predominantly acts as a presynaptic autoreceptor, which suggests involvement in the regulation of neurotransmitter release, possibly influencing migraine pathogenesis." (PMID 40634879, 2025). "More recent studies in rodent models of migraine have further explored a mechanistic role of DRD2 using receptor agonist and antagonists; DRD2 antagonism reversed acute migraine-response metrics including allodynia, CGRP levels, and brainstem c-fos activation." (PMID 40634879, 2025). "Genetic variants in genes such as SLC6A4 (SERT), DRD2 (dopamine receptor), PRDM16 or CYP1A2, and GNB3 have been associated with a modified therapy outcome with triptans in migraine and cluster headache, respectively." (PMID 35222013, 2021). "DRD2 variants were nominally associated with CPSP 4 months after different surgeries, as well as in chronic pain conditions (migraine) and substance abuse/addiction." (PMID 33868360, 2021). "Some epidemiological studies have investigated the relationship between genetic polymorphisms of DRD2, COMT, DBH, and MAO-A and migraine susceptibility, but the results are still inconsistent." (PMID 26632697, 2015). "Haplotype analysis of DRD2 and TH SNPs in 263 migraine patients and 274 unrelated non-migraine controls using the UNPHASED software." (PMID 19772578, 2009). "Interestingly, another study using PET imaging found that interictal endogenous DRD2/D3 availability in the nucleus accumbens of episodic migraine patients is inversely correlated with positive affect, which may explain the underlying emotional aspect of pain in migraine." (PMID 40634879, 2025). "Interestingly, several genes were abundantly expressed already during iDN differentiation and associated with migraine with aura such as HTT, TOR1A but also DRD2 which suggests a putative implication in the development of neural progenitor cells." (PMID 34486248, 2021). "B. Results of the association study of DRD2 rs2283265 and TH rs2070762 in the migraine without aura and migraine with aura subgroups of population 1 and population." (PMID 19772578, 2009). "Studied polymorphisms of DRD2, DBH, and MAO-A genes may not be associated with migraine susceptibility." (PMID 26632697, 2015).
Hypertension (21 papers, 2012 to 2024). The presence of chronic increased pressure in the systemic arterial system. "Human DRD2 SNPs that decrease expression of the receptor are associated with hypertension and increase the susceptibility to chronic kidney disease." (PMID 37762126, 2023). "Several DRD2 single nucleotide polymorphisms (SNPs), including rs6276 and rs6277, are associated not only with elevated blood pressure and hypertension but also with decreased D2R expression and thus function." (PMID 37762126, 2023). "The D2R is important in the regulation of blood pressure because germline deletion of Drd2 in mice causes hypertension that is salt-sensitive." (PMID 33535566, 2021). "In particular, the hypertension in mice with disruption of the dopamine D2 receptor (Drd2) gene (D2−/−) is associated with increased production of reactive oxygen species (ROS)." (PMID 22719934, 2012). "Genetic factors, including polymorphisms of the dopamine D2 receptor gene (DRD2) are associated with essential hypertension, but the mechanisms of their contribution are incompletely understood." (PMID 22719934, 2012). "This DRD2 variant decreases D2R expression in human renal proximal tubule cells and the Taq1A2A2 genotype is associated with hypertension with decreased iliac and tricep skinfold thickness By contrast, the TaqA1 allele frequency is increased in individuals with type 2 diabetes." (PMID 37762126, 2023). "Some somatic changes connected with an elevated blood pressure or even hypertension have been explained by the presence of common single-nucleotide polymorphisms, such as SNPs rs6276, rs6277, and rs1800497 in the DRD2 gene, which cause decreased D2R expression." (PMID 36011589, 2022). "The hypertension in Drd5−/− mice is salt-sensitive, as is the case in Drd2−/− mice." (PMID 33535566, 2021).
alcohol use disorder (20 papers, 2012 to 2025). "More recently, however, a meta-analysis of 62 studies showed a significant association between DRD2 rs 1800497 and Alcohol Use Disorder (AUD)." (PMID 37560184, 2023). "There is a continuing controversy concerning the role of the dopamine D2 receptor gene (DRD2) in association with alcohol use disorder (AUD) and other psychopathologies." (PMID 33171585, 2020). "Is there a biological association between D2 dopamine receptor gene (DRD2) and alcohol use disorder?" (PMID 31702801, 2019). "The DRD2 rs1076560 substitution might be associated with the development of alcohol abuse and drug addiction, which makes it possible to assume a correlation with the development of ICD as an abnormal behavior." (PMID 34945793, 2021). "Whether the dopamine D2 receptor gene (DRD2) is associated with alcohol use disorder (AUD) and other behavioral phenotypes is a long-standing controversy." (PMID 31702801, 2019). "An important marker is represented by DRD2 (dopamine receptor 2), whose hypermethylation is significantly positively correlated to the severity of the alcohol use disorder (AUDIT score: β = 1.139; t648 = 4.289; p = 2.07 × 10−5)." (PMID 41153345, 2025). "In 2021, a study was done on 329 subjects from Lithuania that assessed the effect of Ankyrin Repeat and Kinase Domain Containing 1 - Dopamine Receptor D2 complex (ANKK1-DRD2) and COMT SNP on the risk of alcohol abuse." (PMID 34725583, 2021). "This meta-analysis examines the association between the D2 dopamine receptor gene (DRD2) and alcohol use disorder." (PMID 31702801, 2019). "Szczepankiewicz and colleagues investigated the possible relationship between polymorphisms in the four dopamine receptor genes (−48 A/G in DRD1, −141 C ins/del in DRD2, 9 Ser/Gly in DRD3, and −521 C/T in DRD4) and the comorbidity of alcohol abuse in bipolar patients." (PMID 35893041, 2022).
cocaine addiction (19 papers, 2012 to 2024). "Dop2R encodes a dopamine receptor, and its human ortholog, DRD2, is a well-characterized component of the dopamine reward pathway, which mediates development of cocaine dependence." (PMID 34035044, 2021). "Moreover, numerous studies have verified the association between the DRD2 Taq A1 allele (30 – 40 lower DRD2 numbers) and severe cocaine dependence." (PMID 38766604, 2024). "Moreover, evidence suggests increased risk of relapse in alcohol and cocaine dependence, and heightened heroin, nicotine, and glucose craving when polymorphisms of DRD2 are present or there is low D2 receptor availability." (PMID 31998841, 2020). "The Cocaine Addiction and Dopamine Synapse pathways include tyrosine hydroxylase (Th), L-dopa decarboxylase (Ddc), and dopamine receptor D2 (Drd2), which are involved in the catecholamine biosynthetic pathway and dopaminergic transmission." (PMID 32365077, 2020). "Concerning the known dopamine receptors, it has been reported that DRD1 and DRD2 are the most involved in cocaine addiction, whereas DRD3 and DRD4 are less relevant in the addiction process." (PMID 23285158, 2012). "Similarly, genes that are suggestive of cocaine addiction (KEGG ID: mmu05030) were upregulated in the HFD group compared with the STD group, but the expression of genes that are involved in these pathways (Th/Slc18a2/Drd2) were downregulated (or tempered) in the HF1G group (p = 0.01)." (PMID 35204296, 2022).
Dystonia (19 papers, 2011 to 2026). An abnormally increased muscular tone that causes fixed abnormal postures. "The GOF variant in DRD2, the gene encoding the dopamine receptor 2 (D2R), has been linked to a mixed phenotype of chorea and dystonia." (PMID 38921008, 2024). "We here report the identification of a gain‐of‐function variant in DRD2 that cosegregates with a mixed phenotype of chorea and dystonia in a large Dutch family." (PMID 33200438, 2021). "As a second example, the molecule Chembl372020 [(S)-7-Dipropylamino-5,6,7,8-tetrahydro-indolizine-3-carbonitrile] is linked to two targets/genes, DRD3 (dopamine receptor D3) and DRD2 (Dopamine receptor D2), both involved in dystonia." (PMID 34819133, 2021). "In the present work, we investigated the molecular mechanisms underlying DRD2 reduced levels and altered signaling in the striatum of DYT1 dystonia models, Tor1a+/−‐knock‐out and Tor1a∆gag/+‐knock‐in mice." (PMID 30552094, 2019). "To confirm the involvement of DRD2 dysregulation in DYT1 dystonia, we measured striatal receptor levels in a different model, the Tor1aΔgag/+ mouse." (PMID 30552094, 2019). "Our previous work consistently demonstrated electrophysiological alterations of DRD2 in the population of striatal cholinergic interneurons (ChIs) in multiple DYT1 dystonia models." (PMID 30552094, 2019). "It means that the molecule is significantly involved in dystonia through DRD3 and DRD2 genes." (PMID 34819133, 2021). "Our findings may explain why, despite a clear DRD2 involvement, dopaminergic drugs do not provide clinical benefit in DYT1 dystonia." (PMID 30552094, 2019).
pituitary tumor (19 papers, 2007 to 2026). A benign or malignant neoplasm affecting the pituitary gland. "In the mice pituitary tumor model, we used mice that developed prolactinomas following estradiol treatment or DRD2 deficiencies." (PMID 41655211, 2026). "The loss of DRD2 expression should be investigated as a mechanism allowing the development of larger pituitary tumors." (PMID 30620005, 2019). "To date, homologous deletions of 10 different genes, which are Men1, Cdkn1b, Prkar1a, Rb, Cdkn2b (encoding p19), Drd2, Cdkn2c (encoding p18), Aip, Prl and Prlr, have been reported to yield mouse knockout models for pituitary tumours." (PMID 26320859, 2016). "Studies of other mouse models deleted for genes that were not previously known to be associated with the development of pituitary tumours in man have revealed roles for such genes, which includes Rb, Cdkn2b, Drd2, Prl and Prlr, in pituitary tumourigenesis." (PMID 26320859, 2016). "Dopamine receptor type 2 (DRD2) mediates antitumoral effects in different types of pituitary tumors with variable efficacy." (PMID 37370829, 2023). "The predominant inhibitory receptors of GH-secreting pituitary tumors are somatostatin receptors (SSTRs) and D2 dopamine receptor (DRD2)." (PMID 30620005, 2019). "The inhibitory actions of DA in pituitary tumors are mediated by DA receptor subtype 2 (DRD2) [reviewed in Ref." (PMID 26733942, 2015). "Additionally, in parallel with human medicine, DRD2 expression was correlated with pituitary tumor size in acromegalic cats." (PMID 30620005, 2019). "Similar effects of FLNA on DRD2 regulation were also found in PRL-secreting pituitary tumors." (PMID 26733942, 2015). "In the light of these premises, the aims of the present study were to evaluate in PRL- and ACTH-secreting pituitary tumor cell lines the modulation of FLNA phosphorylation by cAMP pathway activation and DRD2 agonist and to study the effects of P-FLNA on DRD2 intracellular signal transduction." (PMID 33664708, 2020). "Both DRD2 and SSTR5 are also involved in ACTH release in pituitary tumors." (PMID 27856505, 2017). "Recently, a role for cytoskeleton protein filamin A (FLNA) in DRD2 and SSTRs receptors expression and signaling in PRL- and GH-secreting tumors, respectively, has been demonstrated, first revealing a link between FLNA expression and responsiveness of pituitary tumors to pharmacological therapy." (PMID 26733942, 2015).
nicotine dependence (18 papers, 2003 to 2026). Physical and psychological dependence on nicotine. "DRD2 is considered a risk factor for PD, and ANKK1/DRD2 genetic region variants have been associated with nicotine dependence in males in a Chinese study." (PMID 35203939, 2022). "In line with our findings, the combined genetic risk of DRD2 C957T and the DRD2 Taq1 polymorphisms significantly affected both alcohol and nicotine dependence." (PMID 35328003, 2022). "Given the association between DRD2 variants and nicotine dependence mentioned before, smoking behavior should be considered as a potential factor contributing to the observed differences in this study." (PMID 35203939, 2022). "Previous studies identified DRD2 Taq1A A1-allele carriers as vulnerable to developing nicotine dependence." (PMID 26449981, 2015). "One study showed that DRD2 Taq1A seems to be associated with both smoking continuation and progression to nicotine dependence in adolescents." (PMID 26449981, 2015). "In conclusion, results in this research revealed that the rs6275 polymorphism was significantly associated with nicotine addiction susceptibility, suggesting that the DRD2 gene polymorphism had an important effect on the differences in nicotine addiction susceptibility among individuals." (PMID 36082055, 2022). "In addition, the M6275 polymorphism of DRD2 gene was associated with susceptibility to nicotine addiction in Chinese population, and the M6275-C allele had a protective effect on susceptibility to nicotine addiction and smoking initiation." (PMID 36082055, 2022). "This study sought to explore the role of the DRD2 rs1800497 and DRD3 rs6280 polymorphisms in nicotine addiction among patients with treatment-resistant mood disorders and schizophrenia spectrum disorders." (PMID 35455685, 2022). "Hence, a reduced nicotine dependence associated with altered DAT or DRD2 methylation could reflect at least partially an additional endogenous feature of patients susceptible to PD, suggesting that non-smoking may not represent an absolute “actual cause” of the disease." (PMID 35203939, 2022). "The expression of the T allele of the DRD2 rs1800497 and DRD3 rs6280 polymorphisms significantly correlated with a lower level of nicotine dependence and lower use of cigarettes." (PMID 35455685, 2022). "Another example of a genetic influence on nicotine dependence is demonstrated by rs1799732 (−141C Ins/Del) located in the 5’ region of the DRD2 gene." (PMID 31948125, 2020). "Among adolescents who had ever smoked, the likelihood of smoking continuation and nicotine dependence was mostly found to be related to allelic variation in DRD2 Taq1A." (PMID 26449981, 2015). "The present study also examined the effect of smoking history (age at which the participant began smoking and duration of smoking) on the association between SLC6A3, ANKK1/DRD2, and CYP2A6 polymorphisms and nicotine dependence." (PMID 25526961, 2014). "This study provides preliminary results regarding the effect of the SLC6A3 VNTR, ANKK1/DRD2 TaqIA, and CYP2A6*4 polymorphisms on smoking cessation and nicotine dependence in a Japanese population." (PMID 25526961, 2014). "The DRD2 gene and the adjacent ANKK1 gene have been linked to D2R deficits, nicotine dependence, and reward sensitivity." (PMID 24065931, 2013). "This study examined whether functional polymorphisms in SLC6A3, ANKK1/DRD2, and CYP2A6 affect smoking cessation and nicotine dependence in a Japanese population." (PMID 25526961, 2014). "Interestingly, some genes which are considered to be associated with these mental disorders overlap with those which are connected with nicotine dependence (e.g. the D2 dopamine receptor (DRD2) gene)." (PMID 12934961, 2003). "DRD2 rs1800497 and DRD3 rs6280 are involved in nicotine dependence in patients with treatment-resistant mental disorders." (PMID 35455685, 2022).
nicotine dependence (continued). "In the network of genes annotated to the cocaine pathway (also in the nicotine addiction pathway), ADCY5, DRD1, DRD2, PPP1R1B, and protein kinase C β (PRKCB) were over-expressed in Control nursed males relative to all pig groups with exception of Control weaned females." (PMID 35627199, 2022). "Currently, no studies aimed at examining the relationship between DRD2, DRD3, COMT, and OPRM1 polymorphisms, the 5-HTTLPR genotype, and smoking habit and nicotine addiction in patients with treatment-resistant mood disorders and schizophrenia-spectrum disorders." (PMID 35455685, 2022). "We found that current smokers with the 10r/10r genotype were more likely to have low nicotine dependence based on HSI analysis, although the genotypic differences between current and former smokers were not significant for any of the SLC6A3, ANKK1/DRD2, and CYP2A6 polymorphisms." (PMID 25526961, 2014). "We found that current smokers with the SLC6A3 10r/10r genotype were more likely to have low nicotine dependence, based on HSI analysis, although the genotypic differences between current and former smokers were not significant for any of the SLC6A3, ANKK1/DRD2, and CYP2A6 polymorphisms tested." (PMID 25526961, 2014).
dependence (17 papers, 2008 to 2025). "The other polymorphism analyzed in the context is rs1079597 (Taq1B) located in intron 1 of the DRD2 gene and it is noticeably associated with alcohol dependence, as well as other substance dependencies, including nicotine." (PMID 31948125, 2020). "For instance, DRD2 encodes a dopamine receptor, highly relevant to substance dependence." (PMID 38937676, 2024). "Polymorphic variants in the DRD2 gene and D2 receptor may be linked with substance use disorders, dependence and its endophenotypes." (PMID 31948125, 2020). "Additionally, several single nucleotide polymorphisms (SNPs) in the Ankyrin Repeat and Kinase Domain Containing 1 (ANKK1) and Dopamine Receptor D2 (DRD2) genes which are associated with substance dependence have also been found to be associated with ever tanning." (PMID 29649967, 2018). "A statistically significant interaction effect was found between DRD2 rs1076560 genotype and group status (stimulant dependence vs. control) on the Model PCA Main components 1 (F2,509 = 13.30, p < 0.0001, η2 = 0.051)." (PMID 41295441, 2025). "Healthy young adults (18–27 years) with cannabis dependence and without a dependence diagnosis were studied (N = 50/group) in relation to a priori-determined single nucleotide polymorphisms (SNPs) of the DRD2 and PENK genes." (PMID 22745721, 2012). "Previous studies have emphasized the importance of dopamine gene family specifically DRD2 gene as a general risk factor for substance dependence rather than a marker of risk for a particular drug." (PMID 22963930, 2012). "Some of the subjects used other, non-opioid substances besides heroin, however these were not excluded from the study since DRD2 is potentially a non-specific genetic predictor of substance use and dependence." (PMID 23840506, 2013).